EXOC8 (exocyst complex component 8)
Description:
Component of the exocyst complex involved in the docking of exocytic vesicles with fusion sites on the plasma membrane.
Synonyms: SEC84; EXO84; Exo84p; NEDMISB
Tractability: Antibody: its Gene Ontology location is reachable by antibodies, with high confidence. PROTAC: ubiquitination databases record sites on it; its protein half-life has been measured.
Gene: Protein-coding gene on chromosome 1 (231,332,753 to 231,337,852, reverse strand). Ensembl gene ENSG00000116903.
Subcellular location: Cytoplasm; Cytoplasm, perinuclear region; Cell projection, growth cone; Cell projection
Subcellular location (Human Protein Atlas): Cytosol
Pathways (Reactome):
Metabolism of proteins: Insulin processing
Organelle biogenesis and maintenance: VxPx cargo-targeting to cilium
Vesicle-mediated transport: Translocation of SLC2A4 (GLUT4) to the plasma membrane
Gene Ontology:
Molecular function: phosphatidylinositol binding; protein binding; small GTPase binding
Biological process: endosome organization; exocytosis; extracellular matrix disassembly; membrane fission; mitotic cytokinesis; regulation of macroautophagy
Cellular component: exocyst; late endosome; membrane; cytoplasm; cytosol; plasma membrane; cell periphery; growth cone; perinuclear region of cytoplasm
Genetic constraint (gnomAD): Loss-of-function variants: 19 observed, 53.32 expected, observed/expected ratio (o/e) 0.36, 90% interval 0.25 to 0.52. The upper end of that interval is the gene's LOEUF score, 0.52, which puts it in group 2 of 6, group 1 being the genes least tolerant of losing a copy. Missense variants: 781 observed, 954.18 expected, observed/expected ratio (o/e) 0.82, 90% interval 0.77 to 0.87. Synonymous variants: 384 observed, 388.05 expected, observed/expected ratio (o/e) 0.99, 90% interval 0.91 to 1.08.
Homologues: Orthologues: chimpanzee EXOC8 (99% identical), macaque EXOC8 (99% identical), pig EXOC8 (96% identical), guinea pig EXOC8 (93% identical), mouse Exoc8 (93% identical), rat Exoc8 (92% identical), dog EXOC8 (91% identical), tropical clawed frog exoc8 (74% identical), zebrafish exoc8 (73% identical), Drosophila melanogaster Exo84 (27% identical), Caenorhabditis elegans exoc-8 (24% identical).
Diseases named in the same sentence as EXOC8 in open-access papers:
EXOC8 is named in the same sentence as 18 diseases in open-access papers, as found by Europe PMC text mining. Sharing a sentence is not in itself a finding about the gene and the disease. The quoted sentences say what the papers report.
Joubert syndrome (4 papers, 2020 to 2023). Joubert syndrome (JS) is characterized by congenital malformation of the brainstem and agenesis or hypoplasia of the cerebellar vermis leading to an abnormal respiratory pattern, nystagmus, hypotonia, ataxia, and delay in achieving motor milestones. "Of 22 novel variants, a variant in EXOC8 (Exo84) was reported in a patient with Joubert syndrome, a ciliopathy disorder, for the first time." (PMID 37085629, 2023). "It is unclear whether the variant is pathological for Joubert syndrome; however, given its location, the mutation might impair EXOC8 and exocyst function, which in turn might impair trafficking to cilia, resulting in ciliopathy." (PMID 37085629, 2023). "Finally, exome sequencing revealed a mutation in EXOC8 to segregate with disease in a family with Joubert syndrome." (PMID 35265622, 2022).
ciliopathies (3 papers, 2020 to 2025). "Mutations or deletions in genes encoding exocyst proteins, including EXOC2, EXOC4, EXOC7, and EXOC8, have been associated with ciliopathies and neural developmental disorders." (PMID 40777261, 2025).
microcephaly (3 papers, 2021 to 2024). A congenital or acquired developmental disorder in which the circumference of the head is smaller than normal for the person's age and sex. "Exoc7 and Exoc8, subunits of the exocyst complex, are also associated with neurodevelopmental disorders with microcephaly, seizures, and brain atrophy (NEDMISB)." (PMID 38390945, 2024). "Variants in multiple genes regulating endosomal trafficking and/or fusion of secretory vesicles [such as SMPD4, WDFY3, TRAPPC4, RAB18, VPS13B, EXOC7, EXOC8, VPS11], have been associated with the occurrence of microcephaly, cerebral atrophy, and neurodevelopmental delay." (PMID 36538041, 2023).
Meckel-Gruber syndromes (1 paper, 2022). "In addition mutations in EXOC8 and EXOC4 have been implicated in Joubert and Meckel-Gruber syndromes, respectively." (PMID 36150098, 2022).
nephrotic syndrome (1 paper, 2023). A collection of symptoms that include severe edema, proteinuria, and hypoalbuminemia; it is indicative of renal dysfunction. "Mutations in EXOC8 and EXOC2 are associated with neurodevelopmental disorders, and mutations in EXOC6B with skeletal abnormalities and mutations in EXOC4 have been associated with nephrotic syndrome." (PMID 36920342, 2023).
viral infection (1 paper, 2018). "Amongst the identified, 5 proteins (PLVAP, GKN3, EXOC8, SRC8, LRAT) were found to be up-regulated at mRNA level in both adult and P10 mouse brain post viral infection." (PMID 30082709, 2018).
West syndrome (1 paper, 2024). "Among the responders with West syndrome, three out of four patients were identified, with mutations detected in EXOC8 and PEX3 genes." (PMID 39359873, 2024).
cancer (5 papers, 2016 to 2025). A tumor composed of atypical neoplastic, often pleomorphic cells that invade other tissues. "ExoC2 and ExoC8 act as direct effectors of RalA and RalB GTPases, which in turn are Ras effectors liked to several cancers." (PMID 39560727, 2024). "However, TNBC, HER2-enriched and luminal B cancers additionally included exocyst-associated markers (EXOC3, EXOC4, EXOC6B, EXOC7, and EXOC8), which suggested that, unlike luminal A, these cancers not only share dysregulation of ciliogenesis but also dysfunction of transport to cilium." (PMID 40700427, 2025). "These modules contained several cancer regulators such as Intraflagellar Transport (IFT) complex proteins (IFT74, IFT88), BBSome complex proteins (BBS2, BBS7, BBS9, BBS12), exocyst complex components (EXOC3, EXOC4, EXOC6B, EXOC7, and EXOC8), TTC8, TTC21B, EVC, and NEK1." (PMID 40700427, 2025).
neurodevelopmental disorder (3 papers, 2023 to 2024). A behavioral and cognitive disorder with onset during the developmental period that involves impaired or aberrant development of intellectual, motor, or social functions. "Defects in the human homologues of yeast SEC5 (corresponding to human EXOC2), SEC6 (EXOC3L2), SEC8 (EXOC4), SEC15 (EXOC6B), EXO70 (EXOC7), EXO84 (EXOC8), and RHO3 (RALA) are associated with a variety of neurodegenerative and neurodevelopmental disorders." (PMID 39560727, 2024).
EXOC8 also shares sentences with these, for which no sentence is quoted: tumor (4 papers); Brain atrophy (2); Carpenter syndrome (1); Cerebral atrophy (1); developmental delay (1); influenza infection (1); lymph node metastasis (1); Neurodevelopmental delay (1); Seizure (1).